IL1B (interleukin 1 beta)
Diseases named in the same sentence as IL1B in open-access papers (continued):
Sharing a sentence is not in itself a finding about the gene and the disease.
atherosclerosis (continued). "Inflammatory macrophage cluster identified from an atherosclerosis mouse model showed high-level expression of various genes previously assigned to a pro-atherogenic role (e.g., Ccl3, Il1b, Il1a, Nlrp3, Cebpb, Egr1, and Phlda1)." (PMID 38149246, 2023). "For example, it has been described that visceral adipose tissue from patients with metabolic comorbidities show increased expression of IL1β, and IL18 has been associated with atherosclerosis and T2DM." (PMID 37867510, 2023). "AIM2-mediated secretion of IL-1β upregulates IL-17 release by T cells of a murine model of atherosclerosis, which then drives chemokines such as CXC motif chemokine ligand 1 (CXCL1) and CXCL2 to recruit more neutrophils during inflammation." (PMID 36742336, 2023). "TNF-α and IL-8 in GCF showed moderate accuracy in predicting subclinical atherosclerosis, whereas IL-1β in GCF had low accuracy." (PMID 36983201, 2023). "The identification of ‘Atherosclerosis’ and ‘IL-1β’ as an upstream regulator for this shared cohort of genes thereby confirms the presence of an atherosclerotic gene signature." (PMID 38034389, 2023). "SGLT2 inhibitor treatment significantly reduces the expression of inflammatory markers TNF-α, IL-1β, and IL-6, thereby delaying the occurrence and progression of atherosclerosis." (PMID 38274313, 2023). "In vitro results have shown that trelagliptin treatment inhibited the expression of MCP-1, CXCL-1, IL-6, VCAM-1, and ICAM-1 in human aortic endothelial cells exposed to IL-1β, mimicking the microenvironment of atherosclerosis." (PMID 37175496, 2023). "Further, the circulating level of resistin is positively associated with inflammatory biomarkers such as TNF-α, IL-1β, and IL-6, and diseases such as DM2 and atherosclerosis." (PMID 36788619, 2023). "Accordingly, NLRP3 involvement in atherosclerosis has been extensively investigated for its prominent role in mediating the release of both IL-1β and IL-18, which contribute to exacerbating vascular inflammation." (PMID 37830572, 2023). "IL-1β levels are increased in several pathologies that involve oxidative stress and inflammation, including some CVDs such as atherosclerosis and hypertension." (PMID 36937865, 2023). "Small molecule inhibitors selective for NLRP-3, such as MCC950, OLT1177, and CY-09, have been shown to reduce IL-1β production and attenuate atherosclerosis progression in preclinical models." (PMID 37894840, 2023). "Both the crystalline and soluble forms of cholesterol increase macrophage secretion of interleukin 1β (IL-1β), aggravating the inflammatory response in atherosclerosis (AS)." (PMID 36973679, 2023). "IL1B is an important marker of inflammation, and disruption of IL1B homeostasis plays a crucial role in the development of atherosclerosis." (PMID 37268894, 2023). "Monocytes are one of the main producers of IL1β, a cytokine that is known to induce an inflammatory response in vessel wall and is closely related to atherosclerosis as shown by the recent CANTOS trial." (PMID 38096193, 2023). "Canakinumab Anti-inflammatory Thrombosis Outcome Study (CANTOS) demonstrated that inhibition of IL-1β in patients with atherosclerosis can reduce the incidence of major cardiovascular events." (PMID 37581942, 2023). "In parallel, dapagliflozin treatment decreased circulating levels of NLRP3, IL-1β, and IL-18, as well as in the abdominal aorta of ApoE−/− mice with DM and atherosclerosis." (PMID 37175496, 2023). "Additional studies have shown that liraglutide and exenatide decrease the levels of IL-1β, IL-6, TNF-α, and CRP, and the risk of atherosclerosis formation." (PMID 37175496, 2023). "Abnormal immune system response promotes inflammation and inflammatory cytokines (TNFα, IL-6, and IL-1β) that also contribute to the initiation and progression of atherosclerosis and also to the depletion of T cells." (PMID 37627941, 2023).
atherosclerosis (continued). "The inflammatory factors such as IL-1β which are activated by the NLRP3 inflammasome in atherosclerosis activate polymorphonuclear neutrophils, inducing “respiratory burst” and producing a large amount of ROS." (PMID 37155118, 2023). "Atherosclerosis also showed increased levels of IL-1β, caspase 3, and GSDME compared with control vessels, as indicated by immunohistochemistry." (PMID 36807553, 2023). "For example, high levels of plasma IL‐1β were detected in patients with atherosclerosis, which are positively correlated with the severity of the disease and inhibition of IL‐1β‐induced signal transduction alleviates atherosclerosis." (PMID 36633253, 2023). "This encouraging data, along with the pro-coagulant nature and phagocyte recruitment capabilities of IL-1β, prompted the Canakinumab Anti-inflammatory Thrombosis Outcome Study (CANTOS) to determine the role of IL-1β-induced inflammation in atherosclerosis." (PMID 36865918, 2023). "Similar effects on atherosclerosis were shown by the administration of Anakinra, which is a recombinant human IL-receptor antagonist (IL-Ra) that blocks signaling by both IL-1β and IL-1α." (PMID 37446157, 2023). "For example, phosphorylation at S273 by cyclin-dependent kinase 5 (CDK5) has been shown to increase proinflammatory factors including TNF-α, IL-1β, and foam cell formation, which worsen atherosclerosis." (PMID 37833942, 2023). "Lately, it has been revealed that IL-1β helps in leukocyte accumulation and recruitment into atherosclerotic aortas, suggesting its role in speeding up atherosclerosis." (PMID 36851139, 2023). "In high-fat-diet-fed ApoE−/− mice, empagliflozin was reported to activate AMPK, inhibit atherosclerosis progression, and decreased IL-1β and IL-6 levels." (PMID 37373164, 2023). "The role of NLRP3 inflammasome activation in atherosclerosis and atherogenesis can be understood by the role of two terrible cytokines produced by it, i.e., IL-1β and IL-18." (PMID 36851139, 2023). "These genes are involved in cholesterol metabolism (Abca1, Abcg8, Abcg5, Lpl, Cyp7a1, and Pltp), lipid and atherosclerosis (Abca1, Il1b, Ccl2, and Abcg1), bile secretion (Abcg8, Abcg5, and Cyp7a1), and IL-17 signaling pathway (Ccl7, Il1b, and Ccl2)." (PMID 37301941, 2023). "Here, the main focus will be on IL-1β as this is a potent driver of the inflammatory response in atherosclerosis and vascular inflammation." (PMID 35600479, 2022). "NLRP3 inflammasome activation leads to production of active IL-1β and IL-18 as well as pyroptosis, all of which play profound roles in atherosclerosis." (PMID 35641492, 2022). "On the other hand, it enters the endothelium and macrophages and starts succinate/IL-1β signal axis to produce considerable inflammatory factors, thereby exacerbating the inflammatory process of atherosclerosis." (PMID 35273600, 2022). "Our studies reveal that SORBS2 silencing inhibited activation of the NLRP3/ caspase-1/ IL-1β pathway, ultimately blocking the inflammation process in AS, and thus potentially providing protection against hypercholesterolemia and atherosclerosis." (PMID 35590369, 2022). "The pro-inflammatory cytokines TNF-α and IL-1β are known to contribute to the development of atherosclerosis and foam cell formation, further evidencing the detrimental role of PCSK9 in this pathology." (PMID 36012389, 2022). "Elevated levels of CRP, IL-1β, IL-6 and TNF-α in patients with chronic inflammatory diseases stimulate the initiation and accelerate the progression of atherosclerosis, increasing markedly risk of CVD events." (PMID 36297390, 2022).
atherosclerosis (continued). "Previous studies have confirmed that atherosclerosis is mainly attributed to inflammation and the products of pyroptosis such as IL-1β, IL-18, IL-1α, ATP, and GSDMD-N, suggesting crucial role of pyroptosis in the pathogenesis of atherosclerosis." (PMID 36304814, 2022). "This seems important given the role of NLRP3 inflammasome and IL-1β in the pathogenesis of atherosclerosis." (PMID 35163232, 2022). "Inhibition of IL-1β reduced the sizes of formed atherosclerotic plaques and increased plasma IL-10 levels, thereby slowing the onset of atherosclerosis." (PMID 36211578, 2022). "ROS produced by mitochondrion are implicated in chronic inflammation, cancer progression, diabetes mellitus, and atherosclerosis, and it also contributes to LPS-mediated production of pro-inflammatory cytokines IL-1β, IL-6, and TNF-α." (PMID 36012352, 2022). "Recent studies have shown that nucleotide-binding oligomerization domain-like receptor protein 3 (NLRP3) inflammasomes, which are activated by ox-LDL, aggravate atherosclerosis through caspase-1-induced IL-1β secretion." (PMID 36330745, 2022). "miR-652-3p is highly expressed in atherosclerosis, miR-652-3p inhibitor decreased IL-1β, IL-6, and TNF-α expression after ox-LDL treatment." (PMID 36248191, 2022). "Enhanced production of IL6 and IL-1β by macrophages are key to augment inflammatory signaling, contributing to atherosclerosis acceleration." (PMID 35328023, 2022). "A variety of studies confirmed that the innate immune responses mediated by inflammasome-dependent cytokines (like IL-1β) promote the development of CVDs such as atherosclerosis and HF." (PMID 35464402, 2022). "The current findings provide interesting insight into the macrophages-macrophage-like VSMC crosstalk, which would drive functional alterations in the latter cell type through IL-1β/STAT3 axis during atherosclerosis progression." (PMID 36456628, 2022). "Pro-inflammatory cytokines IL-1β, IL-6, and TNFα, released into systemic circulation during active RA, are considered to be the main contributors to atherosclerosis due to their impact on lipid and lipoprotein metabolism, and the biology of the artery wall." (PMID 36297390, 2022). "Bone marrow transplantation of atherosclerosis-prone mice with TET2-deficient bone marrow resulted in an increase in plaque development, which was associated with increases in NLRP3-mediated IL-1β production in TET2-deficient macrophages." (PMID 36613465, 2022). "In clinical trials, the first cytokine inhibition, IL-1β inhibition, was used for atherosclerosis treatment and prevention and achieved results." (PMID 35598196, 2022). "A vicious cycle of IL-1β-mediated NLRP3 inflammasome activation has also been observed in atherosclerosis and amyloid β formation in patients with Alzheimer’s disease." (PMID 35138513, 2022). "In atherosclerosis, inflammasome-mediated IL-1β release promotes an inflammatory environment that promotes disease progression." (PMID 35844498, 2022). "In atherosclerosis, external succinate can trigger the succinate/IL-1β signaling axis and intensify the inflammatory response, which leads to the thickening of atherosclerotic plaques, the fibrosis of artery wall, and the narrowing of the lumen." (PMID 35273600, 2022). "In recent years, interleukin-1β (IL-1β) and interleukin-18 (IL-18) have been identified as the two most important inflammatory cytokines that promote the development of atherosclerosis." (PMID 36589841, 2022). "IL-1β is a pleiotropic cytokine involved in the pathogenesis of atherosclerosis as it is a potent inducer of ICAM and VCAM expression in vascular smooth muscles." (PMID 35928361, 2022).
atherosclerosis (continued). "The major randomized trial on the role of IL-1β inhibition in atherosclerosis, CANTOS, reported a significant reduction in the number of incident cases of lung cancer in patients treated with anti-IL-1β antibody compared to placebo-treated patients." (PMID 36104342, 2022). "WT mice were treated daily with either vehicle or 4μ8c, an IRE1 RNase inhibitor that reduces the IL-1β signaling pathway in atherosclerosis, beginning 2 days prior to LCWE injection." (PMID 35167493, 2022). "This study shows smaller lesions from SMC-specific IL1r1−/− Apoe−/− mice, but also reports signs of instability in these animals and SMC-lineage tracing Apoe−/− mice with advanced atherosclerosis treated with anti-IL-1β." (PMID 35204152, 2022). "This is the first study to report the role of the IL-1β/STAT3 axis in the regulation of macrophage-like VSMCs during atherosclerosis progression." (PMID 36456628, 2022). "It was reported that fucosylation of endothelial mucins regulated IL-1β-induced monocyte-endothelial adhesion, which promoted the initiation and development of atherosclerosis." (PMID 36423178, 2022). "IL-1β blockade has been shown to reduce incident lung cancer in patients with atherosclerosis, putatively preventing pre-existing clinically undetectable nascent tumor clones from progressing." (PMID 36423636, 2022). "Arglabin inhibits the activation of NLRP3 inflammasome in macrophages, thus having an anti-inflammatory effect on atherosclerosis-prone mice by lowering serum levels of IL-1β." (PMID 35563387, 2022). "Since P210-PAM immunization elicited an antigen-specific regulation of CD4+ and CD8+ T cells, we next tested if such regulation involved the IL-1β signaling pathway given the known involvement of this pathway in atherosclerosis." (PMID 35536648, 2022). "Recent results obtained in mice with early atherosclerosis revealed that inhibition of IL-1β and NLRP3 inflammasome reduces leukocyte accumulation in atherosclerotic aortas." (PMID 35310965, 2022). "(iv) AIM2 inflammasome activation and atherogenic proinflammatory factor interleukin-1β (IL-1β) and interleukin-18 (IL-18) release promote inflammatory responses of atherosclerosis." (PMID 35646157, 2022). "IL-1β is involved in the initiation of atherosclerosis as it induces an inflammatory response in endothelial cells, which is reflected by the increased expressions of chemokines and adhesion factors." (PMID 35163364, 2022). "It is roughly understood that inflammation linked with the hyperactivation of cytokines, such as IL-1β, IL-6, IL-10, and TNF-α causes pathogenesis of coronary heart disease and atherosclerosis." (PMID 36289895, 2022). "A previous study showed that PN saponins from PN can suppress atherosclerosis, reduce NF-κB signaling activation and inhibit proinflammatory factors, including IL-6, IL-1β, TNF-α, and Calpain1 protein expression." (PMID 36501304, 2022). "In a murine atherosclerosis model, a 30% reduction in atherosclerotic plaques was shown in the case of IL-1β gene deletion." (PMID 35528818, 2022). "The potential of IL-1β manipulation in atherosclerosis has been known for years, since ApoE−/−/IL-1β−/− mice exhibited significant decreases in aortic sinus atherosclerotic lesions and adhesion molecules expression compared to ApoE−/− only mice." (PMID 36555579, 2022). "Pro-inflammatory cytokines, such as IL-1β, IL-6, and TNF-α play important roles in atherosclerosis progression and are associated with adipokines." (PMID 35566578, 2022). "As downstream effectors of inflammasomes, it has been reported that IL-1α played a key role in the early stage of atherosclerosis, while IL-1β induced inflammation in advanced atherosclerosis in mice." (PMID 35464402, 2022). "Characterisation of macrophages from human carotid artery plaques and in vitro assays reveal that macrophages regulate vascular smooth muscle cell function during atherosclerosis progression through the IL-1β/STAT3 axis." (PMID 36456628, 2022).
atherosclerosis (continued). "MCP-1, IL-1β, and IL-8 are known to play an important role in the pathogenesis of atherosclerosis by stimulating the attraction and adhesion of monocytes." (PMID 35440683, 2022). "TheCanakinumab Anti-inflammatory Thrombosis Outcomes Study (CANTOS) demonstratedreduction of cardiovascular events in patients with atherosclerosis with the useof neutralizing interleukin-1 beta (Il-1beta)." (PMID 39076673, 2022). "Monocytes of patients with atherosclerosis showed a higher glycolytic rate and an increased mRNA expression of IL-6 and IL-1β compared to healthy controls." (PMID 35935635, 2022). "Early growth response 1 (EGR1) is a transcription factor known to enhance the expression of IL1B and chemokines as well as to promote the development of atherosclerosis in mice." (PMID 35246263, 2022). "Triggering human OR6A2 or its mouse orthologue Olfr2 with their cognate ligand octanal induces inflammasome assembly and the secretion of IL-1β, which exacerbates atherosclerosis." (PMID 36311776, 2022). "IL-1β and IL-18 are considered to be the two most prominent inflammatory cytokines in the inflammasome that promote the development of atherosclerosis." (PMID 36589841, 2022). "One study revealed that mitochondrial ROS generated by activated macrophages stimulated the expression of IL-1β, TNF-α, and CCL-2, thereby increasing the risk of developing high-fat-induced insulin resistance and atherosclerosis." (PMID 36558562, 2022). "NLRP3 inflammatory vesicles are large multiprotein complexes that regulate IL-1β production and are essential in the development of atherosclerosis." (PMID 35237603, 2022). "A recent study used scRNA-Seq to define aortic macrophage heterogeneity in atherosclerosis and found that inflammatory macrophages enrichment in Il1b were detectable in atherosclerotic aortas." (PMID 36278486, 2022). "Accumulation of cholesterol crystals in a mouse model of atherosclerosis promotes caspase-1 activation via the NLRP3 inflammasome, triggers IL-1β maturation, and induces pathogenic Th17 differentiation." (PMID 35562903, 2022). "Reverses autophagic dysfunction of plaques, enhances phagocytosis of p62-rich protein aggregates, inhibits macrophage apoptosis and pro-inflammatory IL-1b levels, thereby reducing atherosclerosis." (PMID 35402552, 2022). "Several basic studies have revealed the effect of anti-inflammatory therapy targeting IL-1β on atherosclerosis, as well as its mechanism." (PMID 35566578, 2022). "A protein complex called NLRP3 inflammasome is involved in the release of mature interleukin-1β (IL-1β), which is connected to the initiation and progression of atherosclerosis." (PMID 36671400, 2022). "Among the cytokines IL-17, IL-18 and IL-1β, IL-18 has been reported to be potent in inducing and sustaining inflammatory diseases including atherosclerosis." (PMID 35531433, 2022). "Hyperlipidemia is a major risk factor for atherosclerosis, and the levels of pro-inflammatory cytokines, such as TNF-α, IL-1β, and IL-6, are usually increased and play a vital role during the early progression of atherosclerotic plaques." (PMID 36500975, 2022). "Multiple studies have shown that NLRP3 inflammasome, IL-1β, IL-18 and pyroptosis have a decisive and important role in various diseases, such as DM, atherosclerosis, and Alzheimer’s disease." (PMID 35844498, 2022). "By contrast, the genetic deletion of IL-1β and IL-18 significantly reduced the development of atherosclerosis in ApoE-/- mice." (PMID 34094640, 2021). "Mechanisms of NLRP3/IL-1β regulation and involvement of the pathway in atherosclerosis pathogenesis were covered in recent reviews." (PMID 34440119, 2021). "The activation promoted the production and maturation of IL-1β and IL-18, both of which contribute to atherosclerosis." (PMID 34490270, 2021). "For instance, P. gingivalis was found to be related with atherosclerosis due to the pyroptosis-related release of IL-1β." (PMID 35008798, 2021).